GOLGA2P7 (GOLGA2 pseudogene 7)
Gene: Transcribed unprocessed pseudogene on chromosome 15 (84,203,866 to 84,205,319, reverse strand). Ensembl gene ENSG00000225151.
Diseases named in the same sentence as GOLGA2P7 in open-access papers:
GOLGA2P7 is named in the same sentence as 5 diseases in open-access papers, as found by Europe PMC text mining. Sharing a sentence is not in itself a finding about the gene and the disease. The quoted sentences say what the papers report.
schizophrenia (2 papers, 2018 to 2021). A major psychotic disorder characterized by abnormalities in the perception or expression of reality. "In addition to CSPG4P11, which showed a significant SMR association with schizophrenia in the present study, these included CD46, encoding the CD46 complement regulatory protein, GOLGA2P7, encoding GOLGA2 pseudogene 2, and SLCO4C1, encoding Solute Carrier Organic Anion Transporter Family Member 4C1." (PMID 30419947, 2018).
GOLGA2P7 also shares sentences with these, for which no sentence is quoted: Alzheimer disease (1 paper); amyotrophic lateral sclerosis (1); Insulin resistance (1); Parkinson disease (1).